PER3 (period circadian regulator 3)
Diseases named in the same sentence as PER3 in open-access papers (continued):
Sharing a sentence is not in itself a finding about the gene and the disease.
depression (21 papers, 2009 to 2026). "This study examines the associations between four PER3 SNPs and anxiety, depression, SAD, internalizing disorder (ID), and sleep disturbances." (PMID 41009992, 2025). "In this study, we report multiple associations of single PER3 SNPs with anxiety, depression, sleep disturbance, and internalizing disorder in a population of young adults." (PMID 41009992, 2025). "Genetic polymorphisms in CLOCK and PER3 have since been implicated in psychiatric disorders such as bipolar disorder, major depressive disorder, and attention-deficit hyperactivity disorder (ADHD)." (PMID 40727446, 2025). "In the present study, we found Per3 regulates depression-like behaviors and these were associated with the NAD+-modulated mitochondrial function in the hippocampus of mice." (PMID 39894345, 2025). "Single nucleotide polymorphisms (SNPs) in the PER3 gene have also been associated with aberrant circadian parameters, chronotypes, and mood disorders such as depression." (PMID 39759625, 2024). "The PER3-VNTR genotype was directly associated with depression in both males and females, although it was only directly associated with seasonality in males only." (PMID 38132358, 2023). "The missense mutations decreased PER3 protein levels and PER3 repressor activity, indicating that loss of functional PER3 increases the risk for depression." (PMID 29230328, 2017). "None of the variants from these genes showed evidence for association with depression or its subtypes in the present study, although the SNPs examined in PER3 here are either identical or tag those genotyped in the other studies." (PMID 20174623, 2010). "In addition, PER3 haplotype analysis reveals strong associations with anxiety, depression, ID, and sleep disturbances." (PMID 41009992, 2025). "This SNP (rs57875989) has previously been associated with anxiety and depression, but has also appeared significantly associated with evening chronotype, suggesting that PER3-VNTR may have both direct and indirect effects on mood disorders." (PMID 38132358, 2023). "hPER3-P415A/H417R was generated to express human PER3 with two missense variants that had been identified to cause familial advance sleep phase that is associated with increased depression and seasonality symptoms." (PMID 29230328, 2017). "Thus, we hypothesized that Per3 knockout-induced depression may be associated with impairment of mitochondrial function in the hippocampus." (PMID 39894345, 2025). "Odds ratios were calculated for the six most significant multi-SNP PER3 haplotypes in relation to anxiety, depression, and ID and the four most significant multi-SNP PER3 haplotypes in relation to sleep disturbances." (PMID 41009992, 2025). "This study aims to elucidate the role and mechanism of PER3 in regulating depression-like behaviors in mice." (PMID 39894345, 2025). "•Enhancing NAD+ levels through NAM supplementation or NAMPT activation alleviates depression-like behaviors in Per3 knockout mice." (PMID 39894345, 2025). "Taken together, we suggest Per3 ameliorates depressive disorder through modulating the NAMPT-controlled NAD+-SIRT3 pathway to regulate the mitochondrial energy metabolism in the hippocampus of mice." (PMID 39894345, 2025). "Consistently, hPER3-P415A/H417R transgenic mice also show a mild depression-like phenotype, and Per3 knockout mice also present with depression-like behavior, suggesting a role for PER3 in mood regulation." (PMID 35571019, 2022). "Furthermore, Per3 has been reported to influence mental health, and Per3 knockout mice have been shown to exhibit depression-like behavior." (PMID 39894345, 2025). "Nevertheless, our study did not identify any association between PER3 gene polymorphism and psychiatric assessments, including the Beck depression inventory (BDI) and Beck anxiety inventory (BAI)." (PMID 39759625, 2024).
depression (continued). "Given this overlap, we utilized patient depression scores (BDI) as the outcome for ARACNE analysis to test the hypothesis that PER3-VNTR, CRY1, and ZBTB20 are directly involved in mood regulation." (PMID 38132358, 2023). "Here, we observed that the effects of CRY1, PER3-VNTR, and ZBTB20 were also directly associated with depression, underscoring the possibility that these genes directly impact mood regulation via transcriptional (CRY1, PER3-VNTR) or activational (ZBTB20) regulatory mechanisms." (PMID 38132358, 2023). "Indeed, the PER3-VNTR 4 allele has been associated with anxiety and depression, in addition to evening chronotype." (PMID 38132358, 2023). "Taken together these reports indicate that PER3 may have an important role in the development of chronotype, sleep phenotype, and depression and this will likely guide future research." (PMID 28045078, 2017). "It was also of interest that MSET identified circadian rhythm genes including period circadian clock 3 (Per3) and cryptochrome 2 (Cry2) in maternal mPFC with multiple links to depression, as clock genes are emerging as core contributors to depressive pathology in humans and animal models." (PMID 24765068, 2014). "As a previous study reported that overexpression of Bmal1 can up-regulate the expression of Sirt3 and Sod2, and reduce mitochondrial dysfunction induced by 3-MCPD, in conjunction with our findings, we suspected that SIRT3 might also be involved in the development of depression modulated by Per3." (PMID 39894345, 2025). "In conclusion, our study reveals the specific mechanisms of Per3 ameliorates depressive disorder through modulating NAMPT-controlled NAD+ levels and highlight a critical role for Per3 in mitochondrial energy metabolism by impacting the BMAL1 compound through the NAMPT/NAD+-SIRT3 pathway." (PMID 39894345, 2025). "Interestingly, protective effects of CRY1-GG, PER3-VNTR-4,5, and ZBTB20 genotypes on seasonality and depression were not mediated by chronotype, suggesting some clock variants have direct effects on depressive symptoms related to SAD." (PMID 38132358, 2023). "PER3 VNTR genotypes do not differ significantly across overall average MSF (F2,266 = 3.1, p = 0.737), sleep disturbance (F2,865 = 1.45, p = 0.236), or depression scores (F2,540 = 0.07, p = 0.929)." (PMID 32982844, 2020).
bipolar disorder (20 papers, 2009 to 2025). A disorder of the brain that causes unusual shifts in mood, energy, activity levels and the ability to carry out day-to-day tasks. "Results from Benedetti’s study indicated an association of PER3 VNTR genotypes with the age of onset of bipolar disorder and correlated genotype 5/5 with an earlier onset." (PMID 38992306, 2024). "Previous research has shown that mutations in the clock genes, specifically the timeless homolog gene (TIMELESS) and the period homolog 3 gene (PER3), are linked to mental health conditions such as schizophrenia and bipolar disorder." (PMID 39584972, 2024). "As for PER3, associations between genetic polymorphisms of the gene and mental disorders such as schizophrenia and bipolar disorder have been reported." (PMID 30971765, 2019). "Circadian gene polymorphisms in CLOCK and VIP, and NR1D1, ARNTL and PER3 have previously been associated to human bipolar disorder." (PMID 20856823, 2010). "We were not able to confirm the suggestive evidence we had earlier reported that haplotypes in ARNTL and PER3 were associated with bipolar disorder." (PMID 19166596, 2009). "Variants of PER3 have been associated with bipolar disorder." (PMID 38992306, 2024). "One South Indian study showed that the occurrence of the five repeat alleles of Per3 may be a risk factor for bipolar disorder onset in this ethnic group." (PMID 28468274, 2017). "Some studies reported other clock genes associated with bipolar disorder (such as Bmal1 and Per3)." (PMID 28468274, 2017). "Several core clock genes, such as PER1, PER3, CRY1, and CRY2, have been found to be associated with bipolar disorder." (PMID 39454958, 2024). "This is revealing, as abnormalities in circadian rhythms are considered to play a potential underlying role in bipolar disorder, as many genes associated with bipolar disorder including CLOCK, PER3 and BMAL1 are regulated in a circadian manner." (PMID 37730845, 2023). "Studies in humans have yielded evidence for an association of genetic variants of per2, per3 and cry2 with mood disorders such as SAD (seasonal affective disorder), bipolar disorder and dysthymia, respectively selective characteristics of these conditions." (PMID 26679264, 2016). "Interestingly, there is a negative correlation between gray matter volume in the right hippocampus of bipolar depressive patients and Per3 mRNA levels." (PMID 39894345, 2025). "PER3 is a circadian gene that contains a variable number of tandem repeats (VNTR) which codifies for three genotypes: 4/4; 4/5; and 5/5 and is involved in non-visual response to light, a critical process associated with bipolar disorder onset." (PMID 38992306, 2024). "In particular, Benach and colleagues investigated the possible link among polymorphisms of CLOCK, ARNTL, TIMELESS, and PER3 genes (complex analysis of single polymorphisms and haplotypes–SNP interactions) and the comorbidity of alcohol abuse (AAD) in bipolar disorder patients." (PMID 35893041, 2022). "Those unique to bipolar disorder were also enriched for circadian rhythm (PER3 and RORB)." (PMID 32398742, 2020). "While further studies are required, so far, variations of Per3 have been associated with age of onset of mood disorders, response to treatment and circadian mood variations and Per 3, Bmal1, CLOCK, Nr1d1 and Nr1f2 have all been linked to bipolar disorder." (PMID 23521808, 2013). "Finally, multicenter studies could clarify whether effective environmental factors influence PER3 VNTR genotype functions in the context of bipolar disorder regarding age of onset." (PMID 38992306, 2024). "Recent studies on psychiatric disorder also found a relationship between PER3 VNTR genotype and age at onset of bipolar disorder." (PMID 32913680, 2020).
diabetes (15 papers, 2011 to 2025). "Instead, Per3 polymorphisms show correlations with diabetes susceptibility and infertility through circadian disruption." (PMID 41049554, 2025). "This further reduces the possibility that protein-truncating variants in PER3 cause monogenic diabetes." (PMID 36202929, 2023). "RORα variants are linked with an increased possibility of developing diabetes, while PER3 and RORα polymorphisms increase the risk of MetS in the Taiwanese population." (PMID 35053018, 2021). "PER2 polymorphisms are negatively associated with diabetes, while PER3 polymorphisms are positively associated with obesity." (PMID 35053018, 2021). "Recent studies reported that PER2 and PER3 polymorphisms are associated with diabetes and obesity, metabolic syndrome components." (PMID 35053018, 2021). "Among the other genes, only PER3 had obvious functional relevance for diabetes since a tandem repeat polymorphism has been suggested to be associated with the risk of T2D and Per3 knockout mice have altered body composition and glucose intolerance due to increased adipose mass." (PMID 36202929, 2023). "In the present study, B12 modulated several core clock genes (Bmal1, Cry1, Cry2, Per1, Per3), while other genes were primarily affected by diabetes (Bhlhe40, Hif3a, and Nr1d1)." (PMID 41463345, 2025). "In our study, the transcript levels of BMAL1, PER1, and PER3 were also significantly lower in the diabetes groups compared to the normal control group." (PMID 28352282, 2017). "Diabetes remission following VSG in GK rats is associated with increased expression of Dbp, Per1, Per2 and Per3 and decreased expression of Naps2, Arntl/Bmal1 and Clock, which fit the known feedback loop transcriptional regulation of these genes in the pathway." (PMID 41360887, 2025). "Our results are compatible with a role for UII in glucose homeostasis and diabetes although we cannot rule out the possibility that PER3 gene may underlie the reported associations." (PMID 21559414, 2011). "The mRNA expression of BMAL1, PER1, PER2, and PER3 in leukocytes was observed to be lower in non-diabetic individuals, as compared to those with diabetes." (PMID 37475884, 2023). "A list of 15 known clock genes from the primary (Arntl, Clock, Npas2, Per1, Per2, Per3, Cry1, Cry2), secondary (Nrd1d1, Nr1d2, Rora, Rorb, Rorc), and accessory TTFL loops (Nfil3, Dbp) were selected to investigate the effect of diabetes on their rhythmic expression." (PMID 38039846, 2024).
colorectal cancer (14 papers, 2013 to 2025). A primary or metastatic malignant neoplasm that affects the colon or rectum. "Other polymorphisms located in PER3 were associated with breast, prostate, and colorectal cancers and sleep disorders." (PMID 40534841, 2025). "PER3 was previously demonstrated to play a tumor suppressive role in colorectal cancer and its decreased expression has been associated with incidence and progression of colon cancer." (PMID 33114496, 2020). "The Per3 gene is mostly tied to the circadian rhythm, which influences neuropsychiatric diseases and pathological processes of tumors, such as colorectal cancer and prostatic cancer." (PMID 35087378, 2021). "In addition, PER3 is downregulated in colorectal cancer stem-like cells (CSCs) and in drug-resistant colon cancer cells in vitro, which clearly indicates that deregulation of PER3 expression might be an underlying event in the development of chemoresistance in colon cancer." (PMID 33114496, 2020). "Similar to our study, miR-103 was determined to target a gene (PER3) in colorectal cancer cells, which induces apoptosis of cancer cells, and also, the tumor suppressor genes of DICER and PTEN." (PMID 31049031, 2019). "A vital molecular relationship between miR-103 and PER3 (period circadian clock 3) in human colorectal cancer (CRC) cell lines was confirmed." (PMID 26935418, 2016). "As Per3 has been reported to have a critical role in colorectal cancer stem cells pluripotency, it may be a promising gene for targeting cancer stem cells." (PMID 30374678, 2018). "Recent reports showed miR-103 was expressed in colorectal cancer as an oncogenic miRNA by targeting DAPK, KLF4 and PER3." (PMID 26511107, 2015). "Although it has been reported recently that miR-103 was expressed in colorectal cancer as an oncogenic miRNA by targeting DAPK, KLF4 and PER3, the detail mechanism of miR-103 in colorectal cancer growth and metastasis is still largely unknown." (PMID 24828205, 2014).
prostate carcinoma (13 papers, 2016 to 2026). A carcinoma that arises from epithelial cells of the prostate gland. "More recently, alterations in other specific circadian rhythm gene pathways, specifically PER1 and PER3, were found to be associated with an increased risk of prostate cancer among all men." (PMID 40805144, 2025). "In a large GWAS meta-analyses, genetic variation of PER3 found to be significantly related with the risk of prostate cancer and lung cancer." (PMID 37968308, 2023). "PER3 is also associated with paclitaxel resistance in prostate cancer." (PMID 39011396, 2024). "In prostate cancer stem cells, PER3 has been shown to enhance the expression of BMAL1, resulting in the phosphorylation of β-catenin and subsequent activation of the Wnt/β-catenin pathway." (PMID 40690007, 2026). "Research has shown that PER3 is downregulated in prostate cancer stem cells (PCSS), which in turn enhances their tumorigenicity and ability to form spheroids and colonies in the host body." (PMID 39011396, 2024). "Decreased expression of PER3 in prostate cancer stem cells can increase cancer cell resistance to paclitaxel." (PMID 39011396, 2024). "Other interesting links between the circadian clock and prostate cancer are through retinoic acid-RORα1, PER3, and their control of Wnt signaling." (PMID 38033743, 2023). "Mechanistically, PER3 negatively regulates stemness of prostate cancer stem cells via WNT/β-catenin signaling in the tumor microenvironment." (PMID 37968308, 2023). "Similar to the role of PER2, another recent study using a prostate cancer stem cell (PCSC) model showed that PER3 (period circadian regulator 3) is a negative regulator of CSC biogenesis and phenotype." (PMID 36430659, 2022). "Clinically, PER3 is downregulated in human prostate cancer specimens and PER3 expression levels are highly correlated with the prognosis of the PCa patient." (PMID 33816508, 2021).
Obesity (12 papers, 2017 to 2024). Accumulation of substantial excess body fat. "Azevedo P.G., Miranda L.R., Nicolau E.S., Alves R.B., Bical-hoM.A.C., Couto P.P., Ramos A.V., Souza R.P., Longhi R., FriedmanE., Marco L., Bastos-Rodrigues L. Genetic association of thePERIOD3 (PER3) Clock gene with extreme obesity." (PMID 39440312, 2024). "Several clock genes have been associated with metabolic phenotypes in mice, and human PER3 has been linked with BMI and obesity." (PMID 32116548, 2020). "The present study aimed to evaluate the effects of PM2.5 and PM10 on the methylation profile of the clock genes ARNTL, CLOCK, CRY1, CRY2, PER1, PER2, and PER3 in a population of 200 women with obesity." (PMID 33513987, 2021). "In the present study, conducted in a population of subjects with overweight/obesity, we observed an association between PM exposure measured in the week before the blood drawing and the methylation of circadian cycle genes (i.e., CLOCK, CRY1, CRY2, PER1, PER2, and PER3)." (PMID 33513987, 2021). "Finally, two novel genes, DOCK5 and PER3, which are involved in the regulation of the Akt/MAPK pathway and circadian rhythm, respectively, have VNTRs and INDEL that might be associated with obesity." (PMID 28615046, 2017). "In 17 middle-aged subjects with obesity and normal glucose tolerance who underwent the procedure of the hyperinsulinemic-euglycemic clamp with continuous insulin infusion, the expression of core clock genes PER2 and PER3 was increased." (PMID 36432465, 2022). "In a time-course experiment with white adipose tissue biopsies from people with healthy weight or obesity or T2D, no variation in the rhythm and amplitude of core-clock (PER1, PER2, PER3, DBP, BMAL1, and CRY2), metabolic (PGC1), and clock-related (REVERB) genes could be observed in biopsy tissues." (PMID 37475884, 2023).